GREM1 (gremlin 1, DAN family BMP antagonist)
Diseases named in the same sentence as GREM1 in open-access papers (continued):
Sharing a sentence is not in itself a finding about the gene and the disease.
breast carcinoma (continued). "Furthermore, DHA had an inhibitory effect on the expression of GREM1 in human breast cancer cells." (PMID 32141512, 2020). "However, the induction of EMT by GREM1 and its molecular mechanisms in human breast cancer cells remain unclear." (PMID 32141512, 2020). "In addition, BMP agonists that are engineered to prevent interactions with Grem1, as has been performed for Noggin, or BMP-mimetic small-molecule drugs, could be beneficial in the treatment of breast cancer patients with high Grem1 expression." (PMID 31533776, 2019). "Thus, Grem1 is a key determinant of the mutual interplay between breast cancer cells and CAFs." (PMID 31533776, 2019). "Thus, elevated GREM1 in breast cancer tumors may either originate from normal cells in the tumor microenvironment or from the tumor cells themselves." (PMID 31694641, 2019). "Grem1 could be an attractive therapeutic target to interfere with breast cancer progression." (PMID 31533776, 2019). "Together with other reports that GREM1 can activate epidermal growth factor (EGF) receptor in breast cancer cells and bind to slit guidance ligand-2 (SLIT2) in neurons, a somewhat muddied picture exists of GREM1 biology and signaling in health and disease." (PMID 41033552, 2025). "In human breast cancer cells, DHA inhibits gremlin-1 (GREM1), thereby preventing the activation of the ERK/N-cadherin/Slug axis and partial EMT." (PMID 38732588, 2024). "GREM1 has also been reported to bind to and activate epidermal growth factor receptor (EGFR) in SKBR3 human breast cancer cells that overexpress HER2/EGFR." (PMID 37615860, 2023). "GREM1 further promotes mesenchymal phenotype, stemness, and invasion by disrupting BMP/SMAD signaling in breast cancer cells." (PMID 36624542, 2023). "MMP13 was involved in breast cancer progression induced by ETV4 transcription factor, Golgi membrane protein 1, and gremlin-1 (GREM1)." (PMID 34643237, 2021). "In our previous study, we confirmed that GREM1 promotes breast cancer proliferation through EGFR activation, so we confirmed that the increase in MMP13 expression by GREM1 is through EGFR activation." (PMID 33287358, 2020). "Treatment with XCT790 significantly reduced the mRNA level of GREM1 as well as that of KLK3, one of the ERRα target genes, in MDA-MB-453 and SKBR3 breast cancer cells." (PMID 32572171, 2020). "Therefore, we investigated whether DHA inhibits GREM1 expression in human breast cancer cells." (PMID 32141512, 2020). "Extracellular GREM1 was detected in the collected conditioned media from control breast cancer cells (MDA-MB-453-shCtrl and SKBR3-shCtrl), while it was undetectable in GREM1-depleted cells (MDA-MB-453-shGREM1 and SKBR3-shGREM1)." (PMID 32572171, 2020). "Once expressed by ERRα, GREM1 activates EGFR, the ERRα upstream regulator, and ultimately augments the activity of ERRα in breast cancer cells in a positive feedback mechanism." (PMID 32572171, 2020). "In addition, GREM1 might be a promising therapeutic target for breast cancer metastasis." (PMID 33287358, 2020). "To explore the factors that are responsible for inducing GREM1 expression in CAFs, we analyzed by data mining the expression of TGFB1/2/3 and inflammatory cytokines in breast cancer cell lines as well as in breast cancer tissues." (PMID 31533776, 2019). "Since the source of GREM1 in some of the tumor biopsies likely are CAFs, the proportion of cell lines that make their own GREM1 is relatively large and this may indicate that GREM1 gives them a growth advantage that enrich for such cells among the breast cancer cell lines." (PMID 31694641, 2019). "Using web-based databases we analyzed mRNA expression levels of GREM1 and BMP4 in breast cancer cell lines and a breast cancer patient cohort (TCGA) and found that these two genes are also co-expressed in some tumor cell lines and primary tumors." (PMID 31694641, 2019).
breast carcinoma (continued). "We therefore looked for co-expression of GREM1 and its preferred BMPs, BMP2, BMP4 or BMP7, in human breast cancer cell lines using Expression Atlas." (PMID 31694641, 2019). "To explore the source of GREM1 expression, we stained GREM1 RNA by using in situ hybridization (ISH) in a breast cancer TMA, which comprised 24 matched cases of invasive ductal carcinoma, adjacent tissue, and adjacent normal tissue." (PMID 31533776, 2019). "Similar to GREM1, CD24 correlated with reduced RFS in all breast cancer cases when highly expressed." (PMID 31694641, 2019). "The large majority of human breast cancer cell lines did not express GREM1 in vitro, while breast CAFs expressed GREM1 both in vitro and in vivo." (PMID 36430403, 2022). "High GREM1 expression is related to poorer outcomes in CRC and breast cancer patients." (PMID 33967807, 2021). "A positive correlation between GREM1 and MMP13 expression was observed in breast cancer patients." (PMID 33287358, 2020). "In particular, GREM1 increased ERK activation, suggesting that the GREM1-ERK signaling might play a role in EMT of breast cancer cells." (PMID 32141512, 2020). "We, for the first time, showed that GREM1 could regulate multiple MMPs, especially MMP13, in breast cancer cells." (PMID 33287358, 2020). "Notably, we found a relationship between GREM1 and MMP13 expression in breast cancer metastasis for the first time." (PMID 33287358, 2020). "Taken together, these findings suggest that GREM1 may act as a ligand for EGFR, thereby stimulating the proliferation and growth of breast cancer cells." (PMID 32572171, 2020). "Also, the same study showed that GREM1 promotes EMT and invasion of breast cancer cells in vitro and it is correlated with higher levels of intravasation and extravasation in a zebrafish model." (PMID 32733895, 2020). "Moreover, amplification and/or upregulation of BMPs as well as BMP-antagonists, including NOG, GREM1, GREM2, and CHRD have been reported in breast cancer." (PMID 31694641, 2019). "Expression analysis of clinical breast cancer datasets revealed that high expression of GREM1 in breast cancer stroma is correlated with a poor prognosis regardless of the molecular subtype." (PMID 31533776, 2019). "We also observed that 6% of the tumor biopsies had elevated GREM1 mRNA levels as opposed to 10% of the breast cancer cell lines." (PMID 31694641, 2019). "The large majority of human breast cancer cell lines did not express GREM1 in vitro, but breast CAFs did express GREM1 both in vitro and in vivo." (PMID 31533776, 2019). "None of the epithelial cells of breast cancers included in this study showed GREM1-positive expression." (PMID 31533776, 2019). "Antibodies that neutralize Grem1’s function in the Grem1-BMP interaction have been described, which may be beneficial not only for the treatment of pulmonary arterial hypertension but also for breast cancer (by inhibiting breast cancer progression)." (PMID 31533776, 2019). "The gene alteration data shows that GREM1 mRNA is elevated in approximately 6% of the breast cancer biopsies, and that amplifications are not common for this gene." (PMID 31694641, 2019). "Analyzing the metastatic 66cl4 and non-metastatic 67NR cell lines of the 4T1 mouse mammary tumor model, we found that Grem1 was upregulated in 66cl4 cells and primary tumors." (PMID 31694641, 2019). "GREM-1 was found to be significantly upregulated in cells and primary tumors of metastatic 66cl4 cell line in comparison to the non-metastatic 67NR of the 4T1 mouse mammary tumor model." (PMID 35203511, 2022). "Given that loss of stromal BMPR2 expression increases cytokine production in a mouse model of breast cancer, further studies are warranted to investigate whether mesenchymal BMP signaling, modulated by GREM1 and ISLR, could also be involved in shaping the immunosuppressive tumor microenvironment." (PMID 33197448, 2021).
breast carcinoma (continued). "However, the role of GREM1 in the induction of EMT in human breast cancer cells and the effect of DHA on GREM1-induced EMT remain unclear." (PMID 32141512, 2020). "In addition, we performed a GREM1 rescue experiment with the MDA-MB-453 breast cancer cell line to ensure that the effect of shGREM1 was not due to the off-target effect." (PMID 32572171, 2020). "Therefore, GREM1 is a poor prognostic marker of metastasis-free survival in breast cancer regardless of the subtype." (PMID 31533776, 2019). "CAFs with or without GREM1 knockdown were mixed with these breast cancer cells at a 1:1 ratio." (PMID 31533776, 2019). "Moreover, in the TCGA provisional dataset (cBioportal) there was no overlap between breast cancer biopsies overexpressing GREM1 (n = 61) or ESR1 (n = 44) mRNA (data not shown), further supporting a functional link between GREM1 expression and lack of ER-signaling." (PMID 31694641, 2019).
glioma (26 papers, 2018 to 2025). A benign or malignant brain and spinal cord tumor that arises from glial cells (astrocytes, oligodendrocytes, ependymal cells). "For instance, lncRNA Plasmacytoma variant translocation 1 (PVT1) facilitates glioma by targeting miR-128-3p/Gremlin-1 (GREM1) axis." (PMID 32398968, 2020). "Its function during development is not well understood, although it has been associated with osteogenesis and cardiac development; GREM1 has been associated with increased vascular proliferation and carcinogenesis in diffuse intrinsic pediatric glioma and other gliomas." (PMID 31039818, 2019). "GREM1 expression has also been described in a range of stem cells, including intestinal mesenchymal stem cells, osteochondroreticular cells, and glioma cancer stem cells." (PMID 41033552, 2025). "Research has shown that it can affect the progression of glioma by regulating the signaling pathways of GREM1 and BMP." (PMID 39408808, 2024). "When GREM1 is overexpressed, glioma cells can multiply and metastasize, thus promoting the development of the disease." (PMID 38970064, 2024). "GREM1 secreted by glioma cancer stem cells maintains its own stemness and proliferation, whilst blocking differentiation of glioma cells." (PMID 35883579, 2022). "In glial-tumors such as glioblastoma multiforme, GREM-1 overexpression in the cancer stem cells compartment was found to be crucial for tumor cell growth in vitro and in vivo." (PMID 35203511, 2022). "It was reported that high GREM1 expression in gliomas and cervical cancers played an important role in maintaining the stemness of cancer stem cells." (PMID 35883579, 2022). "LncRNA PVT1 promotes the expression of BMP2 and BMP4 by regulating GREM1 expression and promoting glioma progression." (PMID 35113786, 2022). "The overexpression of PVT1 and downregulation of miR-128-3p provoke the upregulation of gremlin 1 (GREM1), promoting cell proliferation, invasion and migration whilst inhibiting apoptosis in glioma cells." (PMID 34202078, 2021). "On the other hand, increased GREM1 expression facilitates the proliferation of cancer cells in lung adenocarcinoma and glioma." (PMID 33967807, 2021). "For example, LncRNA PVT1 promotes tumorigenesis and glioma progression by regulating the miR-128-3p/GREM1 axis and BMP signaling pathway." (PMID 34408982, 2021). "PVT1 promotes tumorigenesis and cancer progression of glioma via regulation of miR-128-3p/GREM1 Axis and BMP signaling pathway." (PMID 34950662, 2021). "LncRNA PVT1 promoted glioma tumorigenesis and progression by targeting miR-128-3p/GREM1 axis and regulating BMP signaling pathway." (PMID 32009853, 2020). "Grem1 was found to promote cell viability, migration, and invasion in glioma and the invasive phenotype of mesothelioma by activating TGFβ/SMAD signaling." (PMID 31533776, 2019). "GREM-1 overexpression in glioma cell lines also promoted epithelial to mesenchymal transition (EMT) through upregulated expression of E-Cadherin and BMP7, and activation of TGF-β signaling through engagement of BMP receptors I and II." (PMID 29435175, 2018). "GREM1 overexpression has also been detailed in a wide range of human cancers, including colorectal, mesothelioma, gastric, breast, and glioma." (PMID 41033552, 2025). "Moreover, GREM-1 overexpression in glioma cell lines induced EMT by upregulating the expression of E-Cadherin and BMP-7, and activation of TGF-β signaling." (PMID 35203511, 2022). "Thus, the authors showed that GREM1 overexpression promotes proliferation and metastasis of glioma cells, while the use of miR-128-3p mimic inhibits the biological functions of glioma cells by targeting the GREM1 3′-UTR." (PMID 35892126, 2022). "In addition, miR-128-3p expression was suppressed by GREM1 activation in glioma tissues compared to neighboring normal tissues." (PMID 35892126, 2022). "Glioma stem cells secrete GREM1 to promote tumorigenesis through inhibition of BMP signaling." (PMID 33803224, 2021).
glioma (continued). "Glioma cancer stem cells can secrete GREM1 to promote their stem-like features and maintenance." (PMID 33287358, 2020). "Moreover, GREM1 has been confirmed to be closely related to TGF-β/smad pathway in glioma, colon cancer, chronic pancreatitis, as well as renal damage." (PMID 31143092, 2019). "LncRNA PVT1 upregulates miR-128-3p-regulated downstream signal transduction molecules GREM1 and BMP and promotes malignancy and glioma development." (PMID 36793341, 2022). "In glial-tumors such as GBM, GREM-1 overexpression in the cancer stem cells (CSCs) compartment was found to be necessary to maintain tumor cell growth in vitro and in vivo." (PMID 29435175, 2018). "LncRNA PVT1 affects the downstream proteins BMP2 and BMP4, which regulate the bone morphogenetic protein (BMP) signaling pathway, by interacting with miR-128-3p and regulating Gremlin 1(GREM1), thereby affecting glioma cell proliferation, invasion, and migration." (PMID 36479040, 2022). "Furthermore, this lncRNA modulates Gremlin 1 (GREM1) and BMP downstream signaling pathway through sponging of miR-128-3p, thereby promoting tumorigenesis and progression in gliomas." (PMID 33980320, 2021).
hereditary mixed polyposis syndrome (26 papers, 2013 to 2025). "A duplication of approximately 40 kb upstream of the GREM1 gene leads to hereditary mixed polyposis syndrome (HMPS), an autosomal dominant disorder that predisposes untreated patients to develop colorectal cancer at a median age of 47 years." (PMID 38049682, 2023). "Additional syndromes include GREM1-associated hereditary mixed polyposis syndrome (HMPS1), RNF43-associated serrated polyposis, and RPS20 mutations which is a rare cause of hereditary nonpolyposis CRC." (PMID 36707860, 2023). "A duplication that spans the 3’end of SCG5 and the immediate, adjacent upstream region of GREM1 is associated with hereditary mixed polyposis syndrome (HMPS) as well as tumorigenesis in juvenile polyposis." (PMID 33976257, 2021). "A rare inherited condition called hereditary mixed polyposis syndrome (HMPS) is caused by a 40 kb chromosomal duplication event on chromosome 15q13.3 upstream of the GREM1 gene that leads to 2500-fold upregulation of GREM1 mRNA production in the intestine of these patients." (PMID 41033552, 2025). "Consistently, increased epithelial-specific GREM1 gene and protein expression is observed in tumour tissue from patients with hereditary mixed polyposis syndrome (HMPS), caused by a single 40-kb genetic duplication on chromosome 15 in the GREM1 enhancer region." (PMID 31384391, 2019). "Other rare colonic polyposis syndromes for which the genetic basis is known include Cowden syndrome (mutations in PTEN), juvenile polyposis (mutations in SMAD4 or BMPR1A), hereditary mixed polyposis syndrome (mutation in GREM1), and MUTYH-associated polyposis (biallelic mutations in MUTYH)." (PMID 23805267, 2013). "The tumor-promoting effect of GREM1 has been highlighted by its causative role in triggering hereditary mixed polyposis syndrome (HMPS) and CRC." (PMID 28977865, 2017). "In Hereditary Mixed Polyposis Syndrome (HMPS) patients the switch from mesenchymal to epithelial GREM1 expression arises from a germline duplication mutation on chromosome 157, possibly through amplification of upstream enhancer regions, including known CRC predisposition SNP’s8." (PMID 40467544, 2025). "This duplication was found in a large family of Ashkenazi Jews suffering from hereditary mixed polyposis syndrome (HMPS) and the GREM1 locus was attributed to be causal for the histopathology." (PMID 32486027, 2020). "A 40-kb duplication of a region upstream of GREM1 has been associated with hereditary mixed polyposis syndrome (HMPS), and a 16-kb duplication in the regulatory region of GREM1 has been found as the disease-causing genetic alteration in a family with attenuated/atypical polyposis syndrome." (PMID 30563495, 2018). "Recently, genome-wide screening efforts led to the identification of mutations affecting the expression of GREM1 as the cause of hereditary mixed polyposis syndrome (HMPS) and mutations in the POLD1 and POLE genes as the cause of polymerase proofreading-associated polyposis (PPAP) syndrome." (PMID 27279102, 2016). "Similarly, overexpression of GREM1 in Hereditary mixed polyposis syndrome (HMPS) leads to the persistence or reacquisition of stem‐cell properties in LGR5‐negative cells outside the stem‐cell niche." (PMID 40434957, 2025). "Furthermore, aberrant GREM1 expression in the bowel disease, hereditary mixed polyposis syndrome (HMPS), is sufficient to initiate colonic tumorigenesis." (PMID 32756430, 2020). "Hereditary mixed polyposis syndrome (HMPS) is a rare condition characterized by the development of mixed-morphology colorectal tumors and is determined by a 40 Kb genetic duplication, resulting in the aberrant expression of the gene-encoding mesenchymal bone morphogenetic protein antagonist, GREM1." (PMID 29652830, 2018). "However, in hereditary mixed polyposis syndrome (HMPS), a 40 kb genetic duplication causes GREM1 ectopic expression, with consequent destruction of the BMP gradient along the intestinal epithelium." (PMID 29853913, 2018).
hereditary mixed polyposis syndrome (continued). "Overexpression of GREM1 has been described in epithelial cells in a genetic condition called hereditary mixed polyposis syndrome (HMPS), as well as the more common sporadic colorectal serrated adenoma." (PMID 40277903, 2025). "A germline gene duplication event upstream of the GREM1 gene on chromosome 15 leads to amplified GREM1 mRNA expression and hereditary mixed polyposis syndrome (HMPS)." (PMID 37615860, 2023). "Recently, Jaeger and colleagues reported a role for epithelial BMP‐antagonist GREM1 overexpression in hereditary mixed polyposis syndrome (HMPS)." (PMID 28159860, 2017). "GREM1 is a ligand sequestering BMP antagonist, overexpressed in hereditary mixed polyposis syndrome due to a gene duplication event." (PMID 29652830, 2018). "Interestingly, aberrant epithelial GREM1 expression leads to the development of hereditary mixed polyposis syndrome (HMPS) and traditional serrated adenomas." (PMID 28346486, 2017).